ARID1A (AT-rich interaction domain 1A)
Diseases named in the same sentence as ARID1A in open-access papers (continued):
Sharing a sentence is not in itself a finding about the gene and the disease.
tumor (continued). "Recent evidence suggests that ARID1A may have a role in progesterone insensitivity, as loss of ARID1a led to reduced expression of PGR in human endometrial cell lines, mouse models, and clinical tumour tissues." (PMID 38275587, 2023). "The tumor cell cytoplasm was positive for ARID1A expression." (PMID 35151345, 2022). "Together, our data demonstrate that VSV∆51-amiR-4-infected cells induce a bystander effect in the TME by secreting amiR-4-containing SEVs which facilitate tumour cell death via a synthetic lethal interaction between ARID1A and EZH2 with the addition of the small-molecule inhibitor GSK126." (PMID 35393414, 2022). "Afterwards, we explored the relevance of ARID1A in tumour initiation in vivo." (PMID 35167193, 2022). "As such, tumor cells with a luminal origin (AR+ and CK8+ cells, arrow) were found to invade the stromal compartment, supporting that focally invasive cancer develops in Arid1a-deficient prostates." (PMID 36435834, 2022). "In addition, ARID1A can exert a tumor suppressor effect by regulating the function of switching defective/sucrose non-fermenting (SWI/SNF) complex." (PMID 35874743, 2022). "Paradoxically, Arid1a ablation exhibited the inhibitory effects when tumor cells were engrafted in Rag1 null mice, suggesting that possible tumor or innate immune cell mediated mechanisms account for a negative role of ARID1A loss on tumor growth." (PMID 36435834, 2022). "In low MSI/microsatellite stable subtype gastrointestinal cancer (excluding the influence of MSI-H), ARID1A mutant cases still had significantly higher tumor immune activity scores than ARID1A wild type tumors, including high TMB, PD-L1 expression and CTC infiltration." (PMID 35928964, 2022). "Following validation, it indicated the ARID1A mutation may interact with Treg and promote Type-I–IFN–Response pathway to facilitate tumor immune response and better survival outcomes for EC patients." (PMID 36281289, 2022). "Following validation, it indicated that ARID1A mutation may interact with Treg and promote Type-I–IFN–Response pathway to facilitate tumor immune response and better survival outcomes for EC patients." (PMID 36281289, 2022). "Recent data indicate that ARID1A impacts anti-tumor immunity and may influence responses to multiple therapies." (PMID 36077815, 2022). "This may be the reason why knocking out ARID1A reduces proliferation as it may be an oncogene early on and then a tumor suppressor later." (PMID 35379887, 2022). "Five of 46 tumors (10.9%) showed reduced ARID1A expression in tumor cell nuclei." (PMID 36249060, 2022). "Common variants of PTEN, ARID1A, KRAS and CTCF were identified in all regions analyzed, which shared 64.1% of the variants analyzed by targeted sequencing, although more heterogeneity was found among the primary tumor samples from different regions." (PMID 35145232, 2022). "Given that ARID1A is a negative regulator of TERS, loss of its expression caused by inactivating mutations would enhance TERT transcription, conferring a survival advantage for tumor cells by maintaining their telomeres." (PMID 34791836, 2022). "ARID1A inactivation is associated with VIM activation and CDH1 suppression, which might serve as crucial molecules influencing COAD prognosis, accelerate tumour progression, and shorten patients' survival time, and promote metastases of COAD." (PMID 36420658, 2022). "Furthermore, the DNA damage repair-associated inhibitors ATR/ATM in combination with ARID1A-deficiency or BAF complex -inhibition functionally synergize, suggesting a potential synthetic lethal strategy to target tumor cells." (PMID 36361605, 2022). "First, though ARID1A variation is closely associated with the clinicopathologic features of CRC (i.e., TNM stage, tumor location, and histological grade), its role on the prognostic significance of CRC remains controversial among the 23 eligible studies, especially on the survival." (PMID 35421925, 2022).
tumor (continued). "It has been previously proposed that ARID1A may play a relevant role both in tumor initiation and tumor suppression, depending on the context." (PMID 36078038, 2022). "Additionally, we performed a differential protein expression analysis comparing the ACC, NEC-like IDH2 and NEC-like SMARCA4/ARID1A tumor classes against each other." (PMID 36443295, 2022). "However, in a tumor environment with mutated ARID1A, the MVIH inhibition is lifted, affecting CDKN1A expression and ultimately leading to tumor progression." (PMID 36359888, 2022). "ARID1A has lately been recognized as a crucial tumor suppressor gene in diverse cancer types." (PMID 35421925, 2022). "The authors also suggested that ARID1A might be an effective tumor suppressor gene in certain subtypes of CRCs because it affects many genes through its role in chromatin remodeling expression." (PMID 35421925, 2022). "Using the HPA website, we looked at the expression of ARID1A in normal and tumor tissue." (PMID 35028302, 2022). "However, there was a significant correlation between ARID1A mRNA expression and size (p = 0.03), grade (p = 0.03), and stage (p = 0.03) of tumor in a ccRCC study." (PMID 35055428, 2022). "A smaller cohort of tumours was assessed for CD8+ TILs within the tumour epithelium (933 ENOC and 480 CCOC), with ARID1A loss being associated with statistically significant higher CD8+ TILs in ENOC but not in CCOC, although a trend to higher CD8+ TILs was seen." (PMID 35647895, 2022). "Additional research is needed to determine whether similar patterns of ARID1A co-alterations are seen in tumor tissue." (PMID 36077815, 2022). "ARID1A was identified to be a tumor suppressor and a tumor stemness repressor in HNSCC cells." (PMID 36230748, 2022). "Above all, significant ARID1A expression in tumor cell lines was verified." (PMID 35028302, 2022). "EP300/CREBBP inhibitors are being trialled in EP300-, ARID1A- and CREBBP-deficient tumours." (PMID 35267442, 2022). "A significant association between ARID1A loss and MMRd was noted, present in 22% of all ENOC, highlighting that ARID1A loss is probably confounded by MMRd, given MMRd results in a high mutational burden in an otherwise genomically quiet tumour type." (PMID 35647895, 2022). "ARID1A function appears to influence the tumor immune microenvironment and response to ICIs." (PMID 36229854, 2022). "Many reports suggest that ARID1A plays a tumor suppressive role in various cancers." (PMID 35070505, 2022). "Using GEPIA2, similar results were obtained in ARID1A COAD tumour tissues (p = 0.034, r = 0.33)." (PMID 36420658, 2022). "Deficiency of ARID1A has been described to be associated with an increased programmed cell death-ligand 1 (PD-L1) expression, a high tumor mutational burden (TMB), impaired mismatch repair (MMR) and a modulated tumor microenvironment." (PMID 35565222, 2022). "By contrast, the NSMP/L1CAM-negative patients were mainly ER/PR-positive and ARID1A-negative, and showed an intermediate prognosis, likely attributable to a more favorable underlying tumor biology." (PMID 36358847, 2022). "In summary, ARID1A influences the tumor immune microenvironment (TIME) and response to ICIs." (PMID 36229854, 2022). "To better understand ARID1A's role in EMT, we also looked at the possibility of a link between ARID1A and E‐cadherin, a significant epithelial cell adhesion protein that also serves as a tumour suppressor that was found to be downregulated in KO cells when compared to the normal cell group." (PMID 36420658, 2022). "Another case that harbored missense mutations of the exonuclease domain of POLE (P286R and T323A), PIK3CA, ARID1A, and PTEN and a high tumor mutation burden (169 mutations per DNA megabase) achieved a durable response with pembrolizumab but was microsatellite stable." (PMID 36290878, 2022).
tumor (continued). "Further beneficial changes due to increased activity of ARID1A as a tumor suppressor, including improved DNA damage repair, could be among the expected beneficial outcomes of Bex+Carv treatment." (PMID 36078038, 2022). "Furthermore, tumor suppressor genes with a mutational frequency of >10% in cell lines involved SMAD4, SMARCA4, ARID1A, ARID2, and RBM10." (PMID 36013219, 2022). "Tumor specimens from a total of 46 CRC patients were evaluated with respect to ARID1A expression." (PMID 36249060, 2022). "ARID1A is highly expressed in primary HCC, and the overexpression of ARID1A could accelerate tumor initiation." (PMID 36034939, 2022). "ARID1A has a context-dependent oncogenic and tumour suppressive function in HCC." (PMID 36345011, 2022). "In HCC, negative ARID1A expression was significantly associated with larger tumor size, metastasis, shorter recurrence-free survival, and shorter overall survival." (PMID 35669430, 2022). "Arid1a was shown to have a dual role as both oncogene and tumour suppressor in mouse, supporting the hypothesis that epigenetic mechanisms determine specific cellular phenotypes according to the context of the surrounding tissue." (PMID 33732709, 2021). "It was suggested that ARID1A had dual roles in both oncogenicity and tumor suppression in CCA." (PMID 34249744, 2021). "In contrast, the majority of tumours lacking ARID1A mutations showed a weaker, albeit significant, mutational enrichment at TSSs, likely explained by the improved statistical power of the larger set of samples analysed (FDR = 1.2 × 10− 6, FC = 1.09)." (PMID 33941236, 2021). "Signaling pathways related to the roles of ARID1A in tumor initiation and tumor suppression." (PMID 34671561, 2021). "The ARID1A subunit of SWI/SNF chromatin remodeling complexes is a potent tumor suppressor." (PMID 34731603, 2021). "Similarly, in one additional HCC tumour, SA501481, we identified an HBV insertion into chromosome 1 associated with the deletion of one copy of tumour suppressor gene ARID1A." (PMID 34824211, 2021). "In addition, ARID1A and PIK3CA mutations were found to cooperate to promote tumor growth through sustained IL-6 overproduction, and IL-6 was identified as a physiological target of ARID1A tumor suppressor activity." (PMID 33758607, 2021). "Moreover, in endometrial atypical hyperplasia, which demonstrates heterogeneous and patchy loss of ARID1A, higher immunoreactivity for phospho-H2AX, a marker for DSBs, was found in ARID1A-negative tumor foci than in areas with intact ARID1A expression." (PMID 34737943, 2021). "Except for one ARID1A mutated case, in none of the tumor suppressor genes were two mutations of the same gene detected (patient MT-10)." (PMID 34200508, 2021). "Chandler and colleagues were able to generate ARID1A conditional allele, where they observed that although loss of ARID1A promoted embryonic lethality, it did not lead to tumor formation by itself." (PMID 34680390, 2021). "Our findings suggest that the therapeutic targeting of TAMs may be important in enabling CD8 + cells to access the tumour, further enhancing and synergising current immune checkpoint-based immunotherapy in ARID1A mutant patients." (PMID 34359755, 2021).
tumor (continued). "Mutations in ARID1A (p = 0.0205), ARID2 (p = 0.0207), BRAF (p = 0.023) SMARCA4 (p = 0.015), TERT (p = 0.0041), and IDH1 (p = 0.0041) were significantly exclusive to BM while the same variants remained undetected in the corresponding extracranial tumor tissues." (PMID 33578810, 2021). "According to a recent metanalysis, the frequency of ARID1A mutation and ARID1A protein expression loss in CRC patients was approximately 12–13% and was significantly associated with poorly differentiated grade and advanced tumor depth." (PMID 33435234, 2021). "We found no statistically significant tumor-infiltrating lymphocytes (TIL) counts in tumors harboring CNV or somatic oncogenic ARID1A mutations than tumors that were not amplified or mutated in the ARID1A gene." (PMID 34414106, 2021). "In order to explore whether the key genes showed somatic mutations in EC, we detected mutations in tumor-related genes and found PTEN (71.46%), PIK3CA (50.6%) and ARID1A (40.77%) were most frequently mutated genes." (PMID 33495413, 2021). "All these observations about the role of ARID1A in regulating enhancer-mediated gene expression, in tumor suppression and in the regulation of differentiation programs, have encouraged us to investigate the significance of ARID1A alterations in refining the molecular classification of EC." (PMID 33668727, 2021). "There are still some problems to be solved, such as the target genes regulated by ARID1A and the specific mechanisms in tumor suppression, whether other signaling pathways can exert tumor suppression effects, and the prognostic value of ARID1A and patients." (PMID 34136379, 2021). "Furthermore, the increase of ARID1A in tumor cells enhanced the response of inflammatory chemokines." (PMID 34414106, 2021). "In addition, we also showed that ARID1A and PIK3CA mutations frequently co-occur in UCEC tumor samples." (PMID 34941867, 2021). "In addition, ARID1A loss sensitizes cancer cells to PARP inhibitors potentially via inhibition of ATR function in DSB repair, suggesting a new method of targeting tumor cell synthesis to lethality." (PMID 34671561, 2021). "Further studies are required to explore the molecular mechanisms of ARID1A at different stages of carcinogenesis in different cancers, which may help reveal the tumor-initiation or tumor-suppression functions of ARIDIA." (PMID 34671561, 2021). "Our findings that SAHA and valproate interfered with cell viability, cell cycle distribution and cell differentiation in ARID1A mutant PF338 tumor cells strongly support this hypothesis." (PMID 34257602, 2021). "Mutations in ARID1A, ARID2, BRAF, SMARCA4, TERT and IDH1 were significantly exclusive to intracranial metastases while the same variants remained undetected in the corresponding extracranial tumor tissues." (PMID 33578810, 2021). "Moreover, we confirmed the mutation in ARID1A gene (p.R1276∗), ERBB3 (p.S128R), KEAP1 (p.R135H), PALB2 (p.P807S), and NTRK1 (p.Q736X), previously reported by F1CDx, both in the tumor and in the ccfDNAs." (PMID 34178989, 2021). "Utilizing Arid1a-mutated OCCC mice treated with the HDAC6 inhibitor and anti-PD-L1 immune checkpoint blockade, they further found that tumor burden reduced and mice survival improved because of the activation and increased presence of interferon-gamma-positive CD8 T cells." (PMID 34671561, 2021). "ARID1A commonly exerts the tumor-suppressive functions in CCA as well as multiple cancers." (PMID 34249744, 2021). "Mutations with high VAFs indicated early appearance during tumorigenesis or tremendous contribution to later expansion of tumor cells, and the previous study demonstrated AKT1, CBFB, MAP2K4, ARID1A, FOXA1, and PIK3CA mutations have relatively high average VAFs in breast cancers." (PMID 33173047, 2020).
tumor (continued). "ARID1A gene encodes a nuclear protein (BAF250a), which is a subunit of the SWI/SNF chromatin remodelling complex, a critical regulator of differentiation, proliferation, DNA repair, and tumour suppression." (PMID 33276477, 2020). "However, ARID1A has been shown to be the strongest tumor suppressor gene amongst the ARID genes in various cancers and ARID1A is known to have the highest alteration rate among the SWI/SNF subunit genes." (PMID 32045431, 2020). "All tumor samples had complete loss of ARID1B protein expression, but retained ARID1A expression." (PMID 33052929, 2020). "On the contrary, tumours with ANXA1 expression seem to also exhibit higher ARID1A protein levels." (PMID 33276477, 2020). "Imbalances between both complexes can be due to overexpression of EZH2 in undifferentiated cancers, but most commonly occur in cancers by mutations of members of the SWI/SNF complex, such as ARID1A and SMARCA4 that together with SMARCA2 is the ATPase subunit of this tumor-suppressing complex." (PMID 33230143, 2020). "Similarly, ARID1A protein expression was decreased in patient-derived HCC tumor tissues, and that decreased expression was significantly correlated with lymph node and distant metastasis, and poor prognosis." (PMID 33344089, 2020). "Furthermore, there are only 3 and 2 exonic small deletions or insertions in cell line and primary tumor, respectively, including small insertions in both ARID1A and ARID1B genes." (PMID 33052929, 2020). "Interestingly, Arid1a deletion coupled with Pten deletion remarkably accelerated tumor progression by increasing invasiveness and dissemination to the lymph nodes 6 weeks after gene knockout." (PMID 32483112, 2020). "Although the ARID1A–SWI/SNF complex is inactive during tumor growth, this negative association highlights the role of the ARID1A–SWI/SNF complex in cancer development through the suppression of oncogenic YAP1/TAZ activity." (PMID 32390875, 2020). "Among ERGs that could be classified as tumor suppressors, KMT2D, KMT2C, ARID1A, ATRX, CREBBP, and PBRM1 were frequently mutated in many cancer types, whereas oncogenic ERGs were each mutated in specific cancer types, mainly IDH1 in LGG and DNMT3A in LAML." (PMID 32963031, 2020). "In parallel, ARID1A loss was associated with a worse prognosis in several tumours, although its function in BrC is not entirely understood." (PMID 33276477, 2020). "The dual roles in both oncogenicity and tumor suppression of ARID1A were demonstrated in several studies and may contribute to the difference results between studies." (PMID 33344089, 2020). "There was 81% (25/31) of ARID1A mutated-Ov-CCA exhibited advanced tumor stage (stage III-IV), but it was not statistically significant (p = 0.843)." (PMID 33344089, 2020). "With the exception of ARID1A, neither associations between expression loss and clinico-pathological parameters—such as age at diagnosis, tumor size and histological tumor type - nor driver mutations were found." (PMID 33227989, 2020). "ARID1A mutation may involve in CCA progression and predominantly in CCA tumors with high tumor stage." (PMID 33344089, 2020). "Of note, the regulation of PIK3IP1 is dependent on EZH2 methyltransferase and inhibition of EZH2 activity combined with loss of ARID1A expression is synthetically lethal, highlighting a potential therapeutic vulnerability through the use of EZH2 inhibitors in this tumour." (PMID 33053751, 2020). "One BAC sample (9%, 1/11) exhibited loss of ARID1A expression associated with a truncating ARID1A mutation and additional loss of the non-mutated allele in the tumour tissue." (PMID 32198650, 2020).